GPX4 (glutathione peroxidase 4)
Diseases named in the same sentence as GPX4 in open-access papers (continued):
Sharing a sentence is not in itself a finding about the gene and the disease.
keloid (4 papers, 2024 to 2025). An irregularly shaped, elevated mark on the skin caused by deposits of excessive amounts of collagen during wound healing. "Then, our RT-qPCR analysis implicated that SLC7A11 (P < 0.001), GPX4 (P < 0.001), and Nrf2 mRNA (P < 0.001) levels were decreased and TFRC mRNA level was increased in keloid tissues." (PMID 38887622, 2024). "Our results implicated that SLC7A11, GPX4, and Nrf2 were remarkably downregulated and TFRC upregulated in keloid tissues." (PMID 38887622, 2024). "We hypothesized that the increase in GPX4 signaling in keloids may be mediated by exosomes that increase the expression of SLC7A11 in keloids." (PMID 39221144, 2024). "Surprisingly, we discovered that GPX4 was significantly differentially expressed between the keloid and normal skin groups, indicating that ADSC-Exos could be a novel but crucial target for preventing the occurrence and development of KF fibrosis." (PMID 39221144, 2024). "A therapy against keloid induces ferroptosis in keloid fibroblasts via ROS, accompanied by downregulation of SLC7A11 and GPX4." (PMID 39958433, 2025). "Therapeutic targeting with either the ferroptosis inducer RSL3 or iron chelator deferoxamine (DFO) effectively disrupted this pathological network, suppressing GPX4/AMT while restoring interferon responses and attenuating keloid growth in vivo." (PMID 40860189, 2025). "Compared with those of the controls, ADSC-Exos and ADSC-Exos cocultured with si-NC KF inhibited the expression of fibrosis-related genes in keloids and increased the protein expression of SLC7A11 and GPX4." (PMID 39221144, 2024). "ADSC-Exos effectively suppressed keloid fibrosis progression and increased GSH and GPX4 gene expression." (PMID 39221144, 2024). "The gene and protein expression levels of GPX4 and GSH in keloids are lower than those in normal skin." (PMID 39221144, 2024). "Additionally, iron has been demonstrated to accumulate in keloid tissue, along with significant downregulation of SLC7A11, GPX4, and Nrf2 and upregulation of transferrin receptor protein 1 (TFRC)." (PMID 39958433, 2025). "SLC7A11, GPX4, and Nrf2 were downregulated and TFRC was upregulated in keloid tissues and KFs." (PMID 38887622, 2024). "Furthermore, SLC7A11 (P < 0.001), GPX4 (P < 0.001), and Nrf2 (P < 0.001) protein levels were significantly downregulated and TFRC protein level was (P < 0.001) upregulated in keloid tissues." (PMID 38887622, 2024). "SLC7A11, GPX4, and Nrf2 were significantly downregulated and TFRC upregulated in keloid tissues." (PMID 38887622, 2024). "To explore whether ferroptosis is involved in keloid development, we collected keloid tissues (n = 70) from keloid patients and normal skin tissues from healthy controls (n = 40), and iron content and SLC7A11, GPX4, Nrf2 and TFRC levels were determined." (PMID 38887622, 2024). "The results showed that keloid fibrosis was associated with a reduction in GPX4 and GSH, which could not prevent the accumulation of lipid metabolite products during ferroptosis progression in keloids." (PMID 39221144, 2024).
kidney cancer (4 papers, 2021 to 2025). Primary or metastatic malignant neoplasm involving the kidney. "Inhibiting GPX4 transcription can be used as a novel target for treating kidney cancer and reducing cancer migration and invasion." (PMID 40969276, 2025). "The association of CALU with GPX4, HSPA5 and SLC7A11 in the pan-cancer data revealed a significant relationship between CALU and ferroptosis among various tumors, especially the breast, prostate and kidney cancers where ferroptosis was more commonly observed." (PMID 34150647, 2021). "GPX4 expression showed the most significant correlation with immune scores in GBMLGG, SARC, and pan-kidney cancer (KIPAN)." (PMID 41142608, 2025).
kidney stone (4 papers, 2023 to 2025). "The knockdown of CHAC1 significantly reversed the GPX4 and XCT protein deficiency in the mouse kidney stone model, and the upregulation of ACSL4 and CD71 protein was also mildly regained." (PMID 39836526, 2025). "By using the CRISPR-dCas13d-eIF4G platform, researchers enhanced GPX4 expression in renal epithelial cells, which reduced calcium oxalate-induced ferroptosis and kidney stone formation in both human cells and mouse models." (PMID 40636672, 2025). "The experiment also revealed that the stable operation of the single‐vector AAV translational regulatory tool designed for the GPX4 gene could effectively alleviate kidney injury and diminish the extent of ferroptosis in the kidneys of the kidney stone mouse model." (PMID 38380498, 2024). "And we further used the nephrolithiasis gene expression datasets (GSE73680), which found a strong negative association between GPX4 and CHAC1." (PMID 39836526, 2025). "Western blot analysis showed decreased expression of SLC7A11 and GPX4, which are key proteins in the regulation of ferroptosis, and increased expression of the fibrosis-related proteins fibronectin and α-SMA in mice with CaOx kidney stones, with a more pronounced effect over time." (PMID 37893066, 2023).
mesothelioma (4 papers, 2021 to 2025). A usually malignant and aggressive neoplasm of the mesothelium which is often associated with exposure to asbestos. "Furthermore, the GPX4 inhibitor RSL3 selectively induced cell death in a subset of mesothelioma cell lines, particularly those classified as the epithelioid subtype." (PMID 41463232, 2025). "Interestingly, we further found that high expression of SLC7A11 were significantly associated with shortened OS and disease-free survival of KIRP, LIHC, and MESO (mesothelioma), and high expression of GPX4 was significantly correlated with shortened OS and disease-free survival of STAD." (PMID 34722530, 2021). "Building on the functional evidence suggesting that low-dose BFA induces ferroptosis, we next sought to assess the intrinsic ferroptosis sensitivity of mesothelioma cells using RSL3, a direct GPX4 inhibitor." (PMID 41463232, 2025). "In this study, we investigated the ferroptosis sensitivity of mesothelioma cell lines using two distinct inducers: the microbial-derived compound BFA and the GPX4 inhibitor RSL3." (PMID 41463232, 2025). "In the present work, we demonstrated that, after treatments with the new prodrug, significantly lower levels of GPX4 and FTH1 were detected in mesothelioma cells, indicating the activation of ferroptosis, supporting the ultrastructural analysis." (PMID 39204360, 2024).
non-alcoholic fatty liver disease (4 papers, 2022 to 2025). "Non-alcoholic fatty liver disease (NAFLD), like non-alcoholic steatohepatitis (NASH), can be promoted by iron accumulation, lipid peroxidation, GPX4 depletion and inflammatory initiation, which are main processes of ferroptosis." (PMID 35429990, 2022).
oral squamous cell carcinoma (4 papers, 2022 to 2025). "Previous data demonstrated that silencing of circFNDC3B limited GPX4 expression and enhanced ROS, total iron level, and Fe2+ in oral squamous cell carcinoma cells via the miR-520d-5p/SLC7A11 axis." (PMID 35847582, 2022).
ovarian tumor (4 papers, 2023 to 2025). "In cardiomyocytes, 4‐HNE blocks the interaction between glutathione peroxidase 4 (GPX4) and ovarian tumor (OTU) deubiquitinase 5 (OTUD5) by addition and carbonylation, which promotes GPX4 ubiquitination and degradation." (PMID 37552043, 2023). "ARDHEP may induce ferroptosis in ovarian tumor cells and prevent tumor cell growth by upregulating GPX4, increasing intracellular ROS and Fe(2+) buildup, and stimulating cellular oxidative damage." (PMID 39192972, 2024).
polycystic ovary syndrome (4 papers, 2023 to 2025). A disorder that manifests as multiple cysts on the ovaries. "In the endometrium of women with polycystic ovary syndrome (PCOS), too little GPx4 leads to a TGF-β1/SMAD2/3-driven buildup of extracellular matrix and fibrosis." (PMID 41009046, 2025). "Previous studies have demonstrated that metformin can increase the expression of SIRT3 and GPX4, significantly elevate the levels of p-mTOR and p-AMPK, and improve polycystic ovary syndrome in mice by inhibiting ovarian ferroptosis." (PMID 41480421, 2025).
small cell lung carcinoma (4 papers, 2022 to 2026). Small cell lung cancer (SCLC) is a highly aggressive malignant neoplasm, accounting for 10-15% of lung cancer cases, characterized byrapid growth, and early metastasis. "In addition, Fer-1 withdrawal from GPX4 KO but not control mouse small cell lung cancer (SCLC) cell lines readily induced the release of MIF, and treatment of PMLFs with the GPX4 inhibitor RSL3 equally led to a significant MIF release from ferroptotic cells." (PMID 40281125, 2025). "As a control, we could independently confirm that non-neuroendocrine (non-NE) small cell lung cancer (SCLC) presents with a relatively small area under the curve (AUC) and, hence, is highly ferroptosis sensitive in response to the GPX4 small molecule inhibitor ML210." (PMID 41173858, 2025).
spinal cord injury (4 papers, 2022 to 2026). Penetrating and non-penetrating injuries to the spinal cord resulting from traumatic external forces (e.g., WOUNDS, GUNSHOT; WHIPLASH INJURIES; etc.). "In the context of spinal cord injury (SCI), TMP has been shown to alleviate ferroptosis by regulating the expression of GPX4 and ACSL4, thereby promoting functional recovery in SCI." (PMID 40248093, 2025). "In rats with spinal cord injury (SCI), DNP promotes neural recovery and inhibits ferroptosis by upregulating the expression of xCT, GPX4, and GSH." (PMID 40248093, 2025).
subarachnoid hemorrhage (4 papers, 2024 to 2026). A serious neurological disorder characterized by intracranial hemorrhage into the subarachnoid space. "Investigations examining the impact of intense physical activity on the intestines as well as initial brain damage after subarachnoid hemorrhage revealed the preventive benefits of resveratrol and netrin-1, respectively, through the Nrf2/FTH1/GPX4 and PPARγ/Nrf2/GPX4 cascade." (PMID 39036600, 2024).
acute coronary syndrome (3 papers, 2021 to 2023). Signs and symptoms related to acute ischemia of the myocardium secondary to coronary artery disease. "Further clinical studies found that decreasing of plasma GPX4 levels is accompanied with increasing of Neu5Ac levels in acute coronary syndrome patients compared to normal subjects 25, which further indicated that Neu5Ac strongly correlated with GPX4 and may participated in ferroptosis process." (PMID 37771765, 2023).
age-related macular degeneration (3 papers, 2024 to 2026). Age-related loss of vision in the central portion of the retina (macula), secondary to retinal degeneration. "In age-related macular degeneration and retinitis pigmentosa, iron accumulation and decreased Glutathione Peroxidase 4/ Glutathione (GPX4/GSH) levels lead to iron death in retinitis pigmentosa and photoreceptor cells." (PMID 39080199, 2024).
autoimmune hepatitis (3 papers, 2021 to 2023). Hepatitis caused by autoantibodies. "In the S100-induced autoimmune hepatitis (AIH) mouse model, ferroptosis caused hepatitis by downregulating glutathione peroxidase 4 (GPX4), and was inhibited by the Ferrostatin-1 mediated Nrf2/HO-1 signaling pathway." (PMID 35962439, 2022). "AAV8-m-GPX4 was used to interfere with the expression of GPX4 in knockdown normal controls and in the S100-induced autoimmune hepatitis model to verify the role of the GPX4 protein in S100-induced AIH and ferroptosis development." (PMID 34966478, 2021). "GPX4 staining was stronger in the control mouse hepatocytes, and in the S100-induced autoimmune hepatitis model group, GPX4 expression was significantly reduced (P < 0.05)." (PMID 34966478, 2021). "The aims of this investigation were to identify the possible effector functions of ferroptosis, based on glutathione peroxidase 4 (GPX4) regulation in an S100-induced autoimmune hepatitis mouse model and hepatocyte injury models." (PMID 34966478, 2021). "The data presented in our study clearly demonstrate that GPX4 is vital for preventing the deleterious effects of lipid peroxidation and ferroptosis in autoimmune hepatitis." (PMID 34966478, 2021). "In addition, the expression of ferroptosis biomarkers (including COX2, ACSL4, and FTH1) was significantly increased in mice with S100-induced autoimmune hepatitis after specific knockdown of GPX4." (PMID 34966478, 2021). "This suggests that ferroptosis in S100-induced autoimmune hepatitis may be regulated through GPX4." (PMID 34966478, 2021). "The dysregulation of COX2, ACSL4, GPX4, and FTH1 expression, as well as MDA and iron overload levels, suggest an important role for ferroptosis in S100-induced autoimmune hepatitis." (PMID 34966478, 2021).
Azoospermia (3 papers, 2021 to 2025). Absence of any measurable level of sperm,whereby spermatozoa cannot be observed even after centrifugation of the semen pellet. "Nevertheless, some causal links between specific selenoprotein deficiencies and phenotypes (e.g., abnormal thyroid function and deiodinase enzymes; low plasma Se and SELENOP, GPX3; azoospermia and SELENOV, GPX4, TXRND3; myopathy and SELENON) can be made." (PMID 34884733, 2021).
chronic heart failure (3 papers, 2023 to 2025). "GPX4 expression was decreased in a doxorubicin-induced mouse model of acute heart failure, but in our chronic heart failure model, GPX4 protein levels were increased." (PMID 37793777, 2023). "Previous studies by our research group have shown that dapagliflozin has a good therapeutic effect on rabbits with chronic heart failure, but the mechanism of inhibiting ferroptosis and improving chronic heart failure through the regulation of the Nrf2/HO-1/GPX4 signaling pathway remains unclear." (PMID 39874368, 2025).
chronic kidney disease (3 papers, 2022 to 2025). Impairment of the renal function secondary to chronic kidney damage persisting for three or more months. "The SLC7A11/GSH/GPX4 axis is a vital pathway that regulates ferroptosis through cystine metabolism and is closely linked to chronic kidney disease." (PMID 39472936, 2024). "However, the role of GPX4 in cats with chronic kidney disease (CKD) remain largely unknown." (PMID 36214464, 2022).
clear-cell carcinomas (3 papers, 2020 to 2025). "It is worth noting that GPX4 can be a latent therapeutic target in some hard-to-treat cancers such as clear-cell carcinomas (CCCs) that have an intrinsic vulnerability to GPX4 inhibition-induced ferroptosis." (PMID 32103754, 2020).
endometritis (3 papers, 2024). An acute or chronic, usually bacterial infectious process affecting the endometrium. "In this study, we found that ferroptosis is involved in the development of endometritis, and PU significantly inhibits the reduction of expression of ferroptosis‐related proteins GPX4 and SLC7A11 induced by S. aureus." (PMID 39042561, 2024). "The levels of the PRLR, LTF, CLA-DRB3.2, beta defensin, TLR2, TLR4, and CCL5 genes were significantly up-regulated in postparturient goats with endometritis compared to tolerant ones, while the GPX4, GST, SOD3, CAT, and ATOX1 gene patterns demonstrated the opposite tendency." (PMID 39195794, 2024).
enteritis (3 papers, 2020 to 2026). Inflammation of the small intestine. "We assessed the impact of Atg16l1-deficiency on PUFA-induced CXCL1 (C-X-C motif chemokine ligand 1) expression, as this chemokine (besides CXCL2) was potently induced in our model system and contributes to enteritis in Gpx4+/-IEC mice." (PMID 41382985, 2026). "We further studied how Atg16l1 governed PUFA-induced chemokine production in Gpx4-deficient IECs and whether such a mechanism is relevant for PUFA-induced enteritis." (PMID 41382985, 2026). "We observed a similar enteritis severity in male and female Gpx4+/−IEC mice." (PMID 32286299, 2020). "Similarly, α-tocopherol, as well as liproxstatin-1 treatment, protected against enteritis in Gpx4+/−IEC mice induced by a PUFA WD, which was associated with reduced signs of LPO and neutrophil infiltration." (PMID 32286299, 2020). "Although epithelial cell death is not phenotypically characterizing enteritis in intestinal-epithelial-specific Gpx4-deficient mice with or without PUFA exposure, we found that ATG16L1-mediated autophagy is required for the inflammatory phenotype, as similarly reported for ferroptosis." (PMID 41382985, 2026). "Notably, Gpx4+/-IEC;atg16l1-/-IEC double mutant mice were protected against PUFA-induced enteritis and against systemic inflammation when compared to Gpx4+/-IEC mice." (PMID 41382985, 2026). "Similarly, Gpx4+/−IEC mice exposed to a PUFA WD exhibited increased LPO and neutrophilic inflammation, and LPO scavenging with α-tocopherol ameliorated enteritis in both models." (PMID 32286299, 2020). "Moreover, Pam2CSK4 gavage into Gpx4+/-IEC;atg16l1-/-IEC mice (for 7 consecutive days in the last week of exposure to a PUFA-enriched western diet for 3 months) was sufficient to instigate enteritis in this model." (PMID 41382985, 2026). "Notably, rapamycin treatment failed to rescue enteritis in Gpx4+/-IEC mice, but induced enteritis in WT mice exposed to a PUFA-enriched western diet." (PMID 41382985, 2026).
Granuloma (3 papers, 2020 to 2025). A compact, organized collection of mature mononuclear phagocytes, which may be but is not necessarily accompanied by accessory features such as necrosis. "A recent study also demonstrated that mice deficient in GPX4 developed focal granuloma-like neutrophilic enteritis when subjected to a ω-6 polyunsaturated fatty acid (PUFA)-rich Western diet." (PMID 41142608, 2025). "Quantitative analysis of the sections revealed a major elevation in the size of the parenchymal areas as well as Mtb-infected granuloma tissue in the Gpx4-deficient lungs." (PMID 36069923, 2022). "Interestingly, GPX4 expression was found to be diminished in myeloid cells adjacent to the necrotic core of granulomas in human lung biopsy specimens, suggesting that these cells are in the early stages of necrosis." (PMID 36069923, 2022). "Importantly, parallel findings were observed in the B6.Sst1s murine model of Mtb infection that develops human-like hypernecrotic granuloma lesions, demonstrating that similar Gpx4-regulated pathology can arise in mice in addition to primates." (PMID 36069923, 2022).
intestinal tumors (3 papers, 2020 to 2022). "For example, in a study of carcinogen-induced intestinal tumor progression in mice, deletion of Gpx4 in myeloid cells induced the accumulation of ROS and promoted carcinogen-induced intestinal tumor invasion." (PMID 35065965, 2022). "GPX4-knockout in the myeloid lineage stimulated the appearance of intestinal tumors in intestinal epithelial cells." (PMID 33102227, 2020).
ischemic heart disease (3 papers, 2022 to 2025). "Collectively, these data demonstrate the clinical relevance of 4‐HNE and GPX4 in patients with ischemic heart disease and suggest that they may serve as novel therapeutic targets." (PMID 37552043, 2023).